SPRED1 (sprouty related EVH1 domain containing 1)
Diseases named in the same sentence as SPRED1 in open-access papers (continued):
Sharing a sentence is not in itself a finding about the gene and the disease.
A further 10 diseases each share a sentence with SPRED1 in 1 paper.